PARP1 (poly(ADP-ribose) polymerase 1)
Diseases named in the same sentence as PARP1 in open-access papers (continued):
Sharing a sentence is not in itself a finding about the gene and the disease.
tumor (continued). "Pharmacological inhibition of PARP1 by DPQ has been shown to reduce tumor growth and progression in mouse models of liver cancer." (PMID 30271949, 2018). "Immunohistochemistry indicates that radiation necrosis lesions and healthy brain express minimal PARP1, whereas U251 tumors overexpress PARP1 in the nuclei of tumor cells." (PMID 29974335, 2018). "We isolate PARP1 mutants from tumour cells with BRCA1 exon 11 mutations and demonstrate that residual BRCA1 function in these cells allows tolerance of PARP1 loss of function, despite the synthetic lethal relationship between these genes." (PMID 29748565, 2018). "The therapeutic potential of PARP1 inhibitors has been tested in an explant system of primary human tumours, showing that inhibiting PARP1 enzyme leads to a decrease in tumour proliferation." (PMID 29606109, 2018). "Collectively, our findings suggest that lncPARP1 promotes tumor growth through up-regulation of PARP1 in vivo." (PMID 29776974, 2018). "Based on our findings, PARP-1 was inhibited by RAPTA-T resulting in a two-fold drop in VEGF-A secretion by MSTO211H tumor cells." (PMID 29980753, 2018). "At the genomic level, PARP1 was documented to regulate transcription of both tumor suppressors and oncogenes and effectors of metastatic processes (E-cadherin, fibronectin)." (PMID 29306194, 2018). "A previous study showed that TRAIL mediates apoptosis through activation of caspase, cytochrome C release, and PARP-1 cleavage in human tumor cells at acidic pH." (PMID 28884134, 2017). "DR5-dependent apoptosis augments cell death preferentially in resistant tumor cells and recruits PARP1 in DR5-related death signaling." (PMID 29072615, 2017). "The levels of PARP2 transcripts are similar in normal and tumor samples, whereas PARP1 has on average a twofold increase in tumor samples compared to normal samples." (PMID 29259170, 2017). "To characterize the indispensability of neutrophils recruitment for PARP-1-induced tumor cells invading, we next systemically depleted neutrophils and found that the engraftment rates of CBRH-7919-GFP to the liver were decreased in spite of hepatic IR injury." (PMID 29179487, 2017). "Here, the authors provide evidence that PARP1 redistribution and DNA repair in tumor cells depend on the formation of a HSF1–PARP13–PARP1 complex." (PMID 29158484, 2017). "The role of PARP1 has been already investigated in brain diseases, and its overexpression has been reported in various tumour types, such as breast, ovary, skin, colorectum, lung and brain." (PMID 28654422, 2017). "Combination of hyperthermia (HT) with PARP1-i thus creates a possibility to induce synthetic lethality in every tumour type that can be heated locally." (PMID 28427225, 2017). "For instance, PARP1, supporting the transcription of androgen receptor in androgen receptor-positive prostate carcinoma, is necessary for tumor cell proliferation." (PMID 28991194, 2017). "We investigated trabectedin and PARP1 inhibitor synergism in several tumor histotypes both in vitro and in vivo (subcutaneous and orthotopic tumor xenografts in mice)." (PMID 28454547, 2017). "Previous studies showed that TET1 can activate PARP-1/ARTD1 independently of DNA breaks and induce tumor cells apoptosis in multiple tissue types." (PMID 29156803, 2017). "Intriguingly, PARP-1 activity is involved in IR injury and tumor progress, both of which promote HCC recurrence after liver transplantation." (PMID 29179487, 2017). "In this paper, we will not only review PARP1 inhibitors, but also introduce the role of PARP1 in DNA repair, gene transcription, inflammation, cell cycling, and angiogenesis during tumor development." (PMID 28991194, 2017). "The observed results were subsequently validated in other tumor types and by combining PARP1 inhibitors with other cytotoxics characterized by different mechanisms of action." (PMID 28454547, 2017).
tumor (continued). "PARP1 staining was primarily localized in the nucleus of tumour cells, consistent with previous studies." (PMID 28654422, 2017). "While in the limited stage of SCLC, the expression of PARP1 was related to the progression free survival of tumor cells." (PMID 29152079, 2017). "It is possible that PARP-1 up-regulation after liver IR injury promotes recurrence by recruiting circulation tumor cells through disordered chemokines." (PMID 29179487, 2017). "It seems that PARP-1 inhibition was a feasible way to decrease tumor cells homing to liver after IR injury." (PMID 29179487, 2017). "These in vitro findings are in line with in vivo model, in which a decreased tumor growth is observed upon addition of PARP1-i." (PMID 28427225, 2017). "A treatment with cDDP alone, cDDP combined with either PARP1-i or HT, or cDDP combined with both induced a change in the steepness of the curve, indicating that these treatments contributed to tumour control." (PMID 28427225, 2017). "Although PARP inhibitors have been undergoing various clinical trials and the PARP1/2 inhibitor olaparib was approved as monotherapy for BRCA-mutated ovarian cancer, their mode of action in killing tumour cells is not fully understood." (PMID 29262611, 2017). "This is consistent with results obtained in our and other laboratories demonstrating both in vitro and in vivo PARP-1 overexpression during PCa tumor progression." (PMID 29216878, 2017). "Its expression leads to a functional insufficiency in HR which is mediated through inhibition of the BRCA2 tumor suppressor, and subsequently a high sensitivity to small-molecule inhibitors of Poly (ADP-ribose) polymerase 1 (PARP1)." (PMID 28868264, 2017). "In malignancies, downregulating transcription of tumor suppressors by PARP1 can also promote tumor growth and progression." (PMID 28991194, 2017). "In ex vivo biodistribution experiments performed at 2 h post injection, this radiotracer achieved uptake values of 1.82±0.21%ID/g in subcutaneous U87 xenograft tumours, which was proven to be mediated by PARP-1." (PMID 28058462, 2017). "Effects on tumour growth delay range from modest in the groups treated with PARP1-i, HT and HT+PARP1-i to substantial after cDDP alone, PARP1-i + cDDP, PARP1-i combined with HT and the triple modality." (PMID 28427225, 2017). "The results revealed that increased expression of miRNA-9 inhibits tumour growth in mice during the treatment with PARP1 AG014699 inhibitors: (PARP-1 inhibitor plus miRNA-9 agomiR: mean tumor volume = 14.3 mm3, vehicle alone: mean tumor volume = 178.8 mm3)." (PMID 29021870, 2017). "Upregulated PARP1 can enhance the anti-apoptotic property of tumours resulting in resistance to DNA damaging therapeutic agents." (PMID 28654422, 2017). "Olaparib (AZD2281) is a potent inhibitor of PARP-1 and is currently being tested in the clinic in combination with radiotherapy for many tumor indications (breast, lung, prostate, pancreatic and head & neck cancers)." (PMID 29152107, 2017). "The positive predictive value (PPV) was 0.982 and the negative predictive value (NPV) was 0.958 for correct classification of tumor and normal tissue, when the threshold between malignant and normal was set at 6.5% PARP1-positive area." (PMID 26900125, 2016). "We further determined the probability of a tissue sample to be malignant based on its PARP1-positive area and found that the probability of a given tissue area to be tumor increased from 0% to 100% between 5% and 9% PARP1-positive area." (PMID 26900125, 2016). "We also observed differences in PARP1 expression when comparing different tumor stages, albeit these are based on small sample sizes (n = 3 per tumor stage)." (PMID 26900125, 2016). "The same characteristics and circumstances that render PARP1 inhibition so attractive in oncology (selective killing of tumor cells with HRR defects) is also part of what can ultimately lead to loss of effectiveness." (PMID 26959114, 2016).
tumor (continued). "We have demonstrated that the third generation PARP-1 inhibitors rucaparib and olaparib sensitised tumour cells to radiation treatment." (PMID 27515310, 2016). "The increased expression of PARP1 post irradiation also becomes interesting considering combination of radiation therapy with PARP1 inhibitor therapy to mediate synthetic lethality to tumor tissue." (PMID 26808835, 2016). "This increase is in the same range as the increase in PARP1 protein expression, suggesting that PARP1 expression levels can be measured on the whole tumor level using PARPi-FL imaging." (PMID 26808835, 2016). "The anti-tumour effect of PARP-1 inhibitors is not only due to inhibition of PARP-1 catalytic activity." (PMID 27515310, 2016). "Determining the uptake of PARPi-FL macroscopically in freshly excised tumor tissues at 24 and 48 hours after irradiation, we found an increased uptake of PARPi-FL, mirroring the pattern of PARP1 protein expression." (PMID 26808835, 2016). "The expression of PARP1, γH2AX, BRCA1, and BRCA2 were significantly associated with each other and were associated with higher tumor stage and presence of distant metastasis." (PMID 27643881, 2016). "This suggests that simultaneous inhibition of both BRCA2 and PARP1 can prevent the outgrowth of resistant cells in a tumor population with HHR heterogeneity." (PMID 26959114, 2016). "In a set of 62 matched tumor tissues, nuclear PARP1 protein levels were observed in a range of low (0–1+; 37 %), moderate (2+; 37 %) and strong (3+; 26 %) expression." (PMID 27756336, 2016). "The effect of 10 Gy irradiation on PARP1 expression and PARPi-FL uptake was assessed in bilateral FaDu tumor bearing nude mice, where the tumor on the right flank was exposed to 10 Gy using an image-guided microirradiator on day 15 after tumor inoculation." (PMID 26808835, 2016). "Interaction between PARP1 and DNA-PKcs facilitates genomic integrity during V(D)J recombination and prevents tumor development." (PMID 27240471, 2016). "On the average, PARP-1 mRNA expression level (mean = 1.82 ± 0.30) was significantly higher in tumor tissues than in healthy tissues." (PMID 27746584, 2016). "Western Blot analysis were used to investigate the crucial molecules involved in selected signaling pathways associated with apoptosis (caspase-9 and PARP-1), cell survival (ERK 1/2) and tumor progression (Wnt3a and β-catenin)." (PMID 27367907, 2016). "Specifically, our xenograft mouse models showed that PARP1 expression was, with levels of 37.2 ± 3.2% and 28.7 ± 1.7% (for FaDu and Cal 27, respectively), 26-fold and 21-fold higher in tumor tissue than tongue tissue (1.4 ± 0.4%)." (PMID 26808835, 2016). "The use of Parp1 i.e., poly(ADP-ribose) polymerase 1 for the production of iPSCs is now well reported and this has also reduced the tumor forming risk sufficiently." (PMID 27878120, 2016). "The mixture increased apoptosis of tumor cells as indicated by an increased ratio of Bax/Bcl-2 and downstream activation of caspase 7 along with increased cleavage of its substrate PARP1." (PMID 27151407, 2016). "The performance of PARP1 as a classifier for tumor and normal tissue was evaluated using a receiver operating characteristic (ROC) curve." (PMID 26900125, 2016). "Given the unique relationship between PARP1 and HRR status, it is inevitable that PARP1 inhibition alone will select for subclones in tumor cell populations that are proficient for HRR." (PMID 26959114, 2016). "In all cases, intense PARP1 expression as determined by immunohistochemistry (IHC) clearly distinguished tumor from adjacent normal tissue." (PMID 26900125, 2016). "This suggests that simultaneous inhibition of BRCA2 and PARP-1 in heterogeneous tumor populations can prevent selection events and forestall emergence of treatment-resistant clones." (PMID 26959114, 2016). "Among the 112 cases of STSs, age of patients, tumor stage, PARP1 expression, γH2AX-positivity, and CSddrm were independent prognostic predictor for both DSS and EFS." (PMID 27643881, 2016).
tumor (continued). "This concept is supported by clinical evidence demonstrating PARP-1 suppression can delay tumor progression." (PMID 25787974, 2015). "For instance, a potential Parp1 inhibitor, Veliparib (ABT-888), with oral bioavailability and the ability to cross the blood-brain barrier, has proven to suppress tumor progress in BRCA1 deletion and the BRCA2 mutation breast cancer xenograft model." (PMID 26184161, 2015). "Previously, impaired BRCA1/2 genes have been known to play an important role in conferring sensitivity to PARP1 inhibitors, providing a well-accepted DNA repair mechanism for the tumor-suppressive effect of PARP1 inhibitors." (PMID 26540566, 2015). "The purpose of the current study was to gain a better understanding of the behavior of rucaparib by delineating the mechanism of its vasoactivity using rat arterial tissue and tumor-recruited vascular tissue in wild-type and PARP-1-/- mice." (PMID 25689628, 2015). "In fact, most of the clinical trials using PARP inhibitors for the treatment of different tumours that have been performed in the past or are currently being performed are based on the role of PARP-1 in the maintenance of genomic stability and integrity." (PMID 26339143, 2015). "It has been previously reported that PARP-1 supports tumor cell growth, and inhibitors of PARP-1 show potent antiproliferative and proapoptoic effects, holding promise for tumor therapy." (PMID 26314963, 2015). "PARP1 inhibitors sensitize tumor cells to cytotoxic drugs such as the alkylating agent temozolomide (TMZ) and cyclophosphamide and the topoisomerase I inhibitors irinotecan and topotecan." (PMID 26115122, 2015). "Thus, given the tumor-associated transcriptional functions of cyclin D1b, and the herein established link between PARP-1 activity and cyclin D1b expression, it will be critical to determine whether the two transcriptional networks cooperate to promote transformation." (PMID 25787974, 2015). "Emerging evidence show that PARP-1 participates in a broad variety of cellular biological processes, such as transcriptional regulation and tumor angiogenesis, independently of its classical DNA damage repair function." (PMID 26314963, 2015). "Here we show, for the first time, a comprehensive analysis of the activity and expression of PARP1 in a large cohort of CLL tumours." (PMID 26539646, 2015). "As a consequence, the expression of PARP1 is up-regulated to compensate the impaired DNA repair and the tumor cells can survive and progress despite of their presence of DNA damage." (PMID 26540566, 2015). "The expression of PARP1 was detected in 28 (70%) tumor specimens, compared with 16 (40 %) in the normal liver tissue specimens." (PMID 25543761, 2015). "In this case, tumor cells becomeextremely dependent on one of the five other repair systems, with PARP1 beinginvolved in each of them." (PMID 26483957, 2015). "To test the function of PARP-1 in tumor progression in vivo, we used an AML murine model injected with C1498-GFP cells that were selected and maintained by puromycin and detected by flow cytometry." (PMID 26314963, 2015). "The expression of CD95 correlated with the expression of caspase-8, caspase-3 and PARP1 in the tumor specimens (P<0.01)." (PMID 25543761, 2015). "Consistently, multivariate analysis also demonstrated that tumor stage and the expressions PARP1 and FOXO3A are independent prognostic indicators for OS and RFS." (PMID 26540566, 2015). "Consistent with increased tumor suppressor activity, we found increased PARP-1 cleavage in 9AA and 9AA plus Campath-1H treated cells." (PMID 24890041, 2014). "Animals treated with the MGLB diminazene showed a significant inhibition of tumor growth relative to control animals and animals treated with the classical PARP-1 inhibitor Olaparib." (PMID 24504413, 2014). "BMN 673 is a novel PARP1/2 inhibitor with substantially increased PARP-mediated tumor cytotoxicity and is now in later-stage clinical development for BRCA-deficient breast cancers." (PMID 25195882, 2014).
tumor (continued). "It was previously demonstrated that tumor clones selected for resistance to PARPi plus TMZ expressed lower levels of PARP-1 as compared to parental sensitive cells." (PMID 24593254, 2014). "Increased PARP1 expression and/or activity in tumor cells have been demonstrated in many tumor types." (PMID 24616882, 2014). "The tumor cells exhibited significantly higher sensitivity to the two most potent SL analogues with increased apoptosis confirmed by PARP1 cleavage compared to their normal counterpart cells." (PMID 24742967, 2014). "Consistent with increased tumor suppressor activity, we found increased PARP-1 cleavage in 9AA and combination treated cells." (PMID 24890041, 2014). "The protein band of 116 kDa corresponding to intact PARP-1 protein measured in relation to Lamin A/C was 2.13 times larger in tumor than in normal tissue." (PMID 25526641, 2014). "Annexin V/propidium iodide and PARP-1 cleavage assays showed that the porphyrins arrested tumour growth by apoptosis and necrosis." (PMID 24684778, 2014). "Given that many anticancer therapies act by damaging the DNA in tumor cells, investigating the therapeutic potential of agents that block PARP-1, and therefore DNA repair, has generated much interest." (PMID 24880570, 2014). "In total, 3.5% of the transcriptome is regulated by PARP-1 with 60–70% positively regulated, including genes involved in tumor promotion such as JUND, MDM2, HGF, FLT1 (VEGFR1), EGFR, HIF2A (EPAS1), SPP1 (OPN), MMP28, ANGPT2, and PDGF." (PMID 24350055, 2013). "The targeting of PARP1 is showing considerable potential for delivering selective tumour cell kill while sparing normal cells, and offers a scientifically rational clinical application." (PMID 23301673, 2013). "While PARP-1 interaction with these factors promotes pro-tumor signaling, other interactions have the opposite effect." (PMID 24350055, 2013). "Of note, such BRCAness correlates positively with tumor response rates to alkylating chemotherapy drugs like cisplatin – as indeed does PARP1/2 gene knockout in mice – yet negatively with responses to taxane-based chemotherapies." (PMID 24377088, 2013). "In conclusion, infection of tumor cells with Mycoplasma induced signal transduction pathways (i.e., the MAPK pathway including ERK2 and PARP-1) that can cause modifications of essential cellular enzymes such as Topo I and affect their activity." (PMID 24013388, 2013). "Poly(ADP-ribose) polymerase-1 inhibition is considered as a useful therapeutic strategy for the treatment of different tumours." (PMID 23301673, 2013). "Cellular energetics and death signaling are heavily regulated by PARP-1, allowing activity of this protein to serve as a switch between cell fates and to affect both tumor proliferation and therapeutic response." (PMID 24350055, 2013). "Overall, evidence suggests that Parp-1 plays primarily a stimulatory role on transcription, including activation of tumor suppressor genes and a more minor role in gene repression." (PMID 23293602, 2012). "CAF-1/p60, PARP-1 and nestin were expressed in all OSCCs; tumours were assigned to two (low-score and high-score) categories on the basis of the median values of marker expression." (PMID 22882088, 2012). "Presence of a basal level of Caspase-3 and cleaved PARP-1 in the untreated VS tumour samples is indicative of active cell death machinery at a basal level in these tumours." (PMID 23304241, 2012). "Pre-clinical studies have shown that olaparib has the potential to selectively target tumour-specific defects by directly inhibiting PARP-1 and PARP-2, either as monotherapy or in combination with cytotoxic agents." (PMID 22223088, 2012). "Inhibition of PARP-1 sensitizes cells to DNA-damaging agents indicating its potentiality in facilitating tumor therapy." (PMID 22583868, 2012). "The uncleaved p111 PARP-1 isoform was present in large amounts in tumours and metastases, as compared with normal counterparts." (PMID 22882088, 2012).